CPAMD8 (C3 and PZP like alpha-2-macroglobulin domain containing 8)
Synonyms: KIAA1283; VIP; K-CAP; ASGD8
Tractability: Antibody: UniProt places it where antibodies can reach, with high confidence; UniProt predicts a signal peptide or a membrane-spanning region; its Gene Ontology location is reachable by antibodies, with medium confidence. PROTAC: ubiquitination databases record sites on it.
Gene: Protein-coding gene on chromosome 19 (16,892,951 to 17,026,815, reverse strand). Ensembl gene ENSG00000160111.
Subcellular location: Secreted; Cell membrane
Subcellular location (Human Protein Atlas): Focal adhesion sites; Predicted to be secreted
Gene Ontology:
Molecular function: endopeptidase inhibitor activity
Biological process: eye development
Cellular component: extracellular region; plasma membrane
Genetic constraint (gnomAD): Loss-of-function variants: 127 observed, 178.31 expected, observed/expected ratio (o/e) 0.71, 90% interval 0.62 to 0.82. The upper end of that interval is the gene's LOEUF score, 0.82, which puts it in group 3 of 6, group 1 being the genes least tolerant of losing a copy. Missense variants: 1,989 observed, 2,074.7 expected, observed/expected ratio (o/e) 0.96, 90% interval 0.92 to 1. Synonymous variants: 834 observed, 859.06 expected, observed/expected ratio (o/e) 0.97, 90% interval 0.92 to 1.03.
Gene-disease validity (ClinGen):
ClinGen rates the evidence that CPAMD8 causes each of these diseases.
anterior segment dysgenesis 8 (autosomal recessive): Definitive.
Homologues: Orthologues: chimpanzee CPAMD8 (99% identical), dog CPAMD8 (81% identical), pig CPAMD8 (79% identical), tropical clawed frog cpamd8 (62% identical), zebrafish cpamd8 (59% identical), macaque CPAMD8 (23% identical), mouse Mug1 (21% identical), rat Mug1l1 (21% identical), mouse Gm7298 (21% identical), rat Cpamd8 (21% identical), mouse Mug2 (21% identical), guinea pig Mug1 (20% identical). Paralogues in human: CD109 (24% identical), A2M (22% identical), PZP (21% identical), A2ML1 (21% identical), C4A (18% identical), C4B (18% identical), C3 (17% identical), C5 (16% identical).
Diseases named in the same sentence as CPAMD8 in open-access papers:
CPAMD8 is named in the same sentence as 26 diseases in open-access papers, as found by Europe PMC text mining. Sharing a sentence is not in itself a finding about the gene and the disease. The quoted sentences say what the papers report.
glaucoma (6 papers, 2021 to 2026). Increased pressure in the eyeball due to obstruction of the outflow of aqueous humor. "We present a rare case of infantile childhood glaucoma resulting from anterior segment dysgenesis due to a homozygous mutation c.1881delG, p.(Arg627Serfs*6), leading to loss of function in the CPAMD8 gene." (PMID 42074612, 2026). "Follow-up cohort studies of children with childhood or juvenile open-angle glaucoma were found to have a low frequency of CPAMD8 pathogenic variants causing glaucoma, especially when proband families were otherwise asymptomatic for any glaucoma." (PMID 34573386, 2021). "Among the many genes associated with ASD, research on CPAMD8 (C3 and pregnancy zone protein-like alpha-2-macroglobulin domain-containing 8) mutations has been relatively limited, but its association with severe ocular diseases such as ectopia lentis and glaucoma has garnered increasing attention." (PMID 40520996, 2025). "The four enriched genes are expressed in ocular tissues and the presence of ADAMTSL4 and CPAMD8 proteins has been demonstrated in anterior segment structures of the eye involved in glaucoma." (PMID 38891949, 2024). "Information of all candidate genes in both families was obtained through literature and HGMD search, in which only CPAMD8 was previously reported in relation to glaucoma." (PMID 35957697, 2022). "Glaucoma and iris abnormalities, as fundamental manifestations of ASD, were common among most patients, highlighting the necessity for monitoring ectopia lentis in individuals with CPAMD8 truncating mutations." (PMID 40520996, 2025). "In sum, whether CPAMD8 is involved in the immunological abnormalities of iris stroma in some subtypes of glaucoma is unknown." (PMID 35957697, 2022). "It was recently suggested that CPAMD8 variants may be involved in the development of ASD, morgagnian cataract, and different subtypes of glaucoma, including POAG, PACG, and congenital glaucoma." (PMID 35957697, 2022).
cataract (3 papers, 2017 to 2021). Partial or complete opacity of the crystalline lens of one or both eyes that decreases visual acuity and eventually results in blindness. "A nonsense mutation in the CPAMD8 gene (g.5995966C>T) with a recessive mode of inheritance was perfectly associated with congenital Morgagnian cataracts in Red Holstein calves." (PMID 31877171, 2019). "ASD patients with mutations in CPAMD8 mainly suffer from cortical and affected cattle from complete mature cataracts." (PMID 28683140, 2017). "It is very likely that congenital bilateral cataracts may be genetically heterogeneous and not yet known variants in genes other than CPAMD8 and NID1 are involved." (PMID 31877171, 2019). "With immunohistochemistry we confirmed a physiological expression of CPAMD8 in the ciliary body epithelium of the eye in unaffected cattle, while the protein was not detectable in the ciliary body of cattle with cataracts." (PMID 28683140, 2017).
congenital glaucoma (2 papers, 2022). "We did not identify pathogenic or likely pathogenic variants in other genes known to cause congenital glaucoma, including rare variants (allele frequency <0.001) in ANGPT1, CPAMD8, CYP1B1, MYOC, LTBP2, PITX2, SVEP1, and TEK." (PMID 36453543, 2022).
autoimmune disease (1 paper, 2019). A disorder resulting from loss of function or tissue destruction of an organ or multiple organs, arising from humoral or cellular immune responses of the individual to their own tissue constituents. "The genes harboring these mutations, including DGKI, TNFRSF10A, GNGT1, CPAMD8, and BAFF, which are expressed in both eye and brain tissues and/or are related to autoimmune diseases, provide new avenues to evaluate the inherited causes of these devastating autoimmune conditions." (PMID 31161422, 2019).
congenital cataract (1 paper, 2019). "For bilateral congenital cataracts in Red Holsteins a perfectly cosegregating mutation within the CPAMD8 gene (CPAMD8:g.5995966C>T) has been reported." (PMID 31877171, 2019). "We genotyped the CPAMD8:g.5995966C>T variant in Holstein calves affected by congenital bilateral congenital cataracts, their unaffected relatives and randomly selected herd mates." (PMID 31877171, 2019). "The objective of this study was to perform a validation study for the CPAMD8:g.5995966C>T variant in Holstein calves affected with congenital cataracts and in addition, for their unaffected relatives including dams, sires and paternal half-siblings as well as randomly selected herd mates." (PMID 31877171, 2019). "Using whole genome sequencing data from calves with congenital cataracts and wild type for CPAMD8:g.5995966C>T did not reveal variants strongly associated with this phenotype." (PMID 31877171, 2019). "A systematic screening program for breeding animals for the CPAMD8:g.5995966C>T variant will not be very effective to reduce congenital cataracts due to the very low sensitivity of the CPAMD8 candidate mutation to detect unaffected carriers." (PMID 31877171, 2019). "In order to screen for further not yet known variants within candidate genes CPAMD8 and NID1 involved in bovine congenital cataracts, we analyzed whole genome sequencing (WGS) in three affected Holstein calves, two unaffected dams of affected calves and one unaffected herd mate." (PMID 31877171, 2019).
ectopia lentis (1 paper, 2025). "Here we report an 18-year-old male patient with bilateral ectopia lentis and biallelic CPAMD8 variants (NM_015692.5:c.[2801delG];[4552C>T]; NP_056507.3:p.[(Gly934GlufsTer64)];[(Gln1518Ter)])." (PMID 41145435, 2025).
Juvenile glaucoma (1 paper, 2025). Juvenile glaucoma (JG) is a rare autosomal dominant open angle glaucoma, characterized by early onset, severe elevation of intra ocular pressure of rapid progression, leading to optic nerve excavation and when untreated substantial visual impairment . "CPAMD8 variants have been linked to anterior segment dysgenesis associated with both congenital and juvenile glaucoma, with the variants c.4298C>A p.(Thr1433Asn) and c.2352dupC p.(Arg785Glnfs*23) identified in more than one family." (PMID 41011222, 2025).
Marfan syndrome (1 paper, 2025). A disorder of the connective tissue. "Here, we report a patient with EL and systemic manifestations reminiscent of Marfan syndrome (MFS) carrying biallelic CPAMD8 truncating variants." (PMID 41145435, 2025).
multiple sclerosis (1 paper, 2018). A progressive autoimmune disorder affecting the central nervous system resulting in demyelination. "Common variants in CPAMD8 were found among top markers associated with multiple sclerosis." (PMID 29670507, 2018).
pigment dispersion syndrome (1 paper, 2022). Pigment-dispersion syndrome is an eye disorder that occurs when pigment granules that normally adhere to the back of the iris (the colored part of the eye) flake off into the clear fluid produced by the eye (aqueous humor). "This study reported a possible association between CPAMD8 variants and pigment dispersion syndrome/pigmentary glaucoma." (PMID 35957697, 2022).
pigmentary glaucoma (1 paper, 2022). Pigmentary glaucoma is a type of secondary open-angle glaucoma characterized by heavy homogenous pigmentation of the trabecular meshwork, iris transillumination defects, and pigment along the corneal endothelium (Krukenberg spindle). "Pigmentary glaucoma was identified in a total of five patients from the two pedigrees, as were compound heterozygous variants of the CPAMD8 gene." (PMID 35957697, 2022). "Whole-exome sequencing and candidate gene verifications were performed to identify the disease-causing variants; in addition, screening of the CPAMD8 gene was performed on 38 patients of sporadic pigmentary glaucoma." (PMID 35957697, 2022). "No signs of pigmentary glaucoma were found in carriers of monoallelic CPAMD8 variant/variants." (PMID 35957697, 2022).
head and neck tumor (1 paper, 2025). "Tumor and normal tissue microarray data (NPC, GSE12452, GSE53819; head and neck tumor, the Cancer Genome Atlas) revealed that AK4 was the only gene that was upregulated in both NPC and head and neck tumor samples compared to normal samples among the gene signatures (AK4, CPAMD8, DDAH1, and CRTR1)." (PMID 40593461, 2025).
CPAMD8 also shares sentences with these, for which no sentence is quoted: anterior segment dysgenesis (2 papers); Alzheimer disease (1); atherosclerosis (1); cancer (1); cognitive disorder (1); inflammatory bowel disease (1); kidney cancer (1); male infertility (1); osteoporosis (1); Parkinson’s (1); primary open-angle glaucoma (1); rheumatoid arthritis (1); Tumor (1); WAGR syndrome (1).